EGFR (epidermal growth factor receptor)
Diseases named in the same sentence as EGFR in open-access papers (continued):
Sharing a sentence is not in itself a finding about the gene and the disease.
cancer (continued). "Also, skin biopsies from cancer patients exhibited increased epidermal MHC class I protein expression during therapy with an EGFR inhibitor." (PMID 29458371, 2018). "Moreover, nuclear EGFR phosphorylates Keap1 and reduces its nuclear protein level, stabilizing nuclear Nrf2 and increasing its transcriptional activity in cancer cells." (PMID 30595797, 2018). "Moreover, EGFR has been proposed as a crucial molecular target for cancer therapy, promoting considerable research into the development of pharmacological inhibitors of EGFR." (PMID 29482638, 2018). "Increased levels of EGFR gene expression are observed in human cancers." (PMID 29239135, 2018). "EGFR in malignant tumors is thought to be a promoter of cancer cell migration and invasion." (PMID 30373614, 2018). "Targeting of MUC1 inhibits EGFR signaling and reduces EGFR-mediated cancer growth." (PMID 29987260, 2018). "This might reflect the challenging issue for EGFR-targeted therapy in general since resistance inevitably occurs even though the antagonists are used in many types of cancer." (PMID 29455655, 2018). "Similarly to EGFR, HER2, encoded by the ERBB2 gene, is also often overexpressed in cancer and its deregulation is associated with aggressive phenotype and shortened survival." (PMID 29455660, 2018). "Interfering with lysosomal function by the inhibition of the vacuolar H+-ATPase, which is essential for lysosomal acidification, was recently demonstrated to abrogate excessive EGFR and Ras signaling in cancer cells, leading to reduced migration and proliferation." (PMID 29303993, 2018). "Chemotherapies including EGFR-TKI induce functional autophagy in diverse cancer cells types." (PMID 30497501, 2018). "Indeed, silencing of CCAT1 led to downregulation of many genes involved in cancer cell proliferation, survival and metastasis, such as EGFR, CDK4, YES1, PAK4, and HMGA1." (PMID 30190462, 2018). "Finally, to illustrate the functional importance of ST6Gal-I in regulating EGFR-dependent survival, cells were treated with gefitinib, an EGFR inhibitor widely used for cancer therapy." (PMID 29402301, 2018). "In addition to genetic alternations associated with tumorigenesis, cigarette smoking behavior was also associated with the insensitivity to EGFR TKIs and poor progression‐free survival (PFS) in different types of cancer patients with EGFR overexpression." (PMID 29570930, 2018). "EGFR is an important target for therapeutic intervention in patients with cancer." (PMID 30425998, 2018). "EGFR is considered to be an important target for multiple cancer therapies." (PMID 29552307, 2018). "An emerging aspect that could be exploited for cancer treatment is the study of how membrane trafficking can influence the outcome of EGFR‐targeted therapies." (PMID 29124875, 2018). "Furthermore, a positive clinical outcome is reported for a cancer patient treated with an anti-EGFR mAb and anti-NGcGM3 therapy." (PMID 29844873, 2018). "In order to evaluate if our formulations are toxic in normal cells we used a non-tumoral epithelioid human cell line (HEK-293) that expresses low level of EGFR33, in which ANANAS formulation showed no significant activity suggesting a certain preference toward EGFR-overexpressing cancer cells." (PMID 30287819, 2018). "Suppression of the EGFR-mediated signaling pathway is used in cancer treatment." (PMID 29548337, 2018). "Thus, inhibition of the EGFR signaling pathway can inhibit the proliferation and metastasis of cancer cells." (PMID 29435193, 2018). "MUC1 and galectin-3 are both commonly over-expressed by solid tumours and their interactive effects on EGFR activation may have an important influence on EGFR-mediated tumourigenesis and cancer progression, and on the effectiveness of EGFR-targeted therapy." (PMID 28731466, 2017). "EGFR and its ligands are frequently up-regulated in human cancers." (PMID 28460454, 2017). "As with FR, EGFR expression is also upregulated in various types of cancer." (PMID 28218708, 2017).
cancer (continued). "Therefore, regulation of EGFR has been deemed as an important strategy for the development of cancer therapy." (PMID 29250520, 2017). "Dysregulation of receptor tyrosine kinases (RTKs) doesn't show potential of increasing p110β level in cancer tissue, furthermore the expression of p110β in tumors with EGFR mutation is lower than in tumors without EGFR mutation." (PMID 29277178, 2017). "Integrin/EGFR-ERK/MAPK signaling pathway also has a critical role in EMT of various cancers." (PMID 29072694, 2017). "EGFR plays a crucial role in malignant cell growth, proliferation and survival of cancer cells." (PMID 28938010, 2017). "The erythroblastosis oncogene B (ErbB) receptors such as epidermal growth factor receptor (EGFR/ErbB1/HER1) and ErbB2, also known as HER2 or p185c-neu, are implicated and overexpressed in the development of many types of cancer, and undergo several alterations in human cancers." (PMID 29050225, 2017). "As degradation of EGFR is essential for adequate regulation of proliferative signals, our findings are also of significance for human hyperproliferative diseases, especially cancers." (PMID 28581508, 2017). "Consequently, huge resources have been engaged to the widespread genotyping of Ras in all cancer patients scheduled for anti-EGFR therapy." (PMID 28578404, 2017). "An increased level of FSH as well as the absence of estradiol induces the higher epidermal growth factor (EGFR) mRNA expression; elevated EGFR activity initiates the DNA synthesis and cell proliferation by converging with the estrogen receptors, resulting in the development of cancer." (PMID 28356910, 2017). "Taken together, we could demonstrate that the treatment of cancer cells with inhibitors targeting EGFR signaling can have different outcomes." (PMID 29296175, 2017). "However, the mutations of EGFR-downstream proteins, such as KRAS in A549, result in drug resistance, protecting cancer cells from therapeutic treatments." (PMID 28787001, 2017). "The expression of EGFR in the tissue was neither associated with the presence/absence of cancer in the biopsies (p=0.950) nor with the CTCs status (p= 0.255)." (PMID 29050295, 2017). "Mutations or fusions of both EGFR and ALK may be primary causes of cancer, whereas both the EGFR gatekeeper mutant T190M and MET may generate drug resistance." (PMID 29086093, 2017). "We sought to elucidate the mechanism of AKT activation in CRC cells by examining many pathways that have been reported for regulating AKT in cancer cells [such as EGFR, IGFR, FGFR, and MET], and found that none of these pathways were activated in CRC cells by CM from LPECs (data not shown)." (PMID 28453235, 2017). "Several anti-cancer therapies target the epidermal growth factor receptor (EGFR)." (PMID 28729680, 2017). "This suggests that CD200 exerts by interacting with a yet unknown receptor of cancer cells, whose activation triggers a pro-apoptotic signal cascade only upon EGFR-TKI treatment, through a pathway distinct from PI3K-Akt and/or ERK signaling." (PMID 28429795, 2017). "In conclusion, we demonstrate a novel function of XIAP BIR domain in regulating cancer cell anchorage-independent growth ability through the upregulation of EGFR translation via the inhibition of miR-200a transcription through the Rac1/PP2A/MAPKK/MAPK/c-Jun axis." (PMID 28057023, 2017). "Thus, the use of radionuclide molecular imaging of EGFR expression would make cancer treatment more personalized." (PMID 28729680, 2017). "By contrast, cetuximab, a monoclonal antibody directed against EGFR, shows a clinical benefit in cancer patients who overexpress EGFR in a manner independent of EGFR mutations." (PMID 28938622, 2017). "Epidermal growth factor receptor (EGFR) is a cancer-driven gene in tumorigenesis." (PMID 28915650, 2017).
cancer (continued). "It is known that EGFR is overly active in many cancers and that IKKα genetic/epigenetic downregulation and cytoplasmic sequestration can trigger oncogenic pathways, of which the regulators of sequestration remain unknown." (PMID 28122935, 2017). "A previous study showed that inhibiting Src activity may inhibit EGFR downstream signaling pathways, thereby inducing cancer cell apoptosis." (PMID 29132432, 2017). "Also, the authors will show the evidence that ncRNAs not only contribute to cancer cells migration and invasion, but also take charge of the resistance of chemotherapy, radiotherapy and EGFR-TIKs." (PMID 28415568, 2017). "According to the Cancer Cell Line Encyclopedia, EGFR mutations possibly impairing the effect of lapatinib are not described for HCC38." (PMID 29100507, 2017). "Moreover, the inhibitory effect of combination therapies with EGFR TKIs and potassium channel blockers on the viability of cancer cells has been measured." (PMID 28219421, 2017). "Moreover, low EZH2 expression was independently associated with shorter PFS in patients with cancer, suggesting that EZH2 expression is a useful additional prognostic biomarker for anti-EGFR therapy." (PMID 28147317, 2017). "EGFR is identified as cellular protooncogene and is overexpressed in a variety of human cancers." (PMID 28316978, 2017). "In contrast, many molecular-targeted drugs against alternative signaling molecules have been developed, and several combinations of EGFR TKIs with these drugs have been found to exhibit synergistic effects against EGFR TKI-resistant cancer in preclinical studies." (PMID 29140271, 2017). "It is noteworthy that EGFR inhibitors, well known drugs used in cancer treatment, may be also beneficial in curing ALI triggered by infection and LPS." (PMID 28460454, 2017). "Co-culture of HPV+ cervical ME180 and CaSki cancer epithelial cells with CAFs in vitro also enhanced epithelial cell proliferation, and this was dependent on production of an epidermal growth factor receptor (EGFR) ligand, the heparin-binding epidermal growth factor-like growth factor (HBEGF)." (PMID 28792475, 2017). "Given that EGFR can act as anoncogenic driver and phosphorylate a variety of cancer-promoting factors, we speculated whether it is also capable of directly regulating the key enzymes involved in lipid metabolism." (PMID 28724430, 2017). "Collectively, these results support our hypothesis that both CMP and cordycepin inhibit cancer cells mitosis and EGFR signaling." (PMID 29212184, 2017). "This implies that EGFR signaling is involved in anti-cancer drug-resistance conferred by CAGE." (PMID 28099142, 2017). "It is unknown whether treatment with imgatuzumab or the combination with cetuximab increases EGFR internalization and/or reduces membranous turnover of EGFR in cancer cells, potentially diminishing ADCC responses." (PMID 28467975, 2017). "However, there are a variety of potential cancers in which EGFR inhibitors are less effective but clinically significant in which its toxicities (primarily acneiform rash) are a significant drawback." (PMID 29069801, 2017). "Resistance to EGFR-TKIs usually develops over time and makes them unable to control cancer; however, the mechanisms that enable this drug resistance remain unknown." (PMID 28507201, 2017). "Taken together, we propose that STAT3 may be an ideal candidate to target cancer invasion, metastasis and EGFR-TKI resistance." (PMID 29221162, 2017). "Various therapies such as PARP inhibitors, anti-androgen therapy, PI3K inhibitors, MEK inhibitors, inhibitors of the cancer stem-cell population, EGFR inhibitors and HDAC inhibitors have been explored to cure TNBC patients because of the lack of specific TNBC therapies." (PMID 28947965, 2017).
cancer (continued). "Whilst PTs with FA-like areas harbor highly recurrent MED12 exon 2 mutations and less common genetic alterations in bona fide cancer genes, most PTs without FA-like areas are MED12-wild-type and display more frequent genetic alterations targeting cancer genes, in particular EGFR." (PMID 29043292, 2017). "Both EGFR and ErbB2 play an important role in regulating cancer stemness." (PMID 29156633, 2017). "On the other hand, the extract inhibited the phosphorylation of EGFR in PC-3 cancer cells." (PMID 28694778, 2017). "Thus, we propose our new strategy in this report by using the GNP-conjugated EGF ligand to target EGFR-expressing cancer cells for NTP irradiation." (PMID 28887524, 2017). "EGFR represents a key therapeutic target for cancer treatment." (PMID 28731466, 2017). "EGFR is overexpressed in many cancers and regulates cancer invasion, metastasis, and angiogenesis." (PMID 28423672, 2017). "Likewise, we observed that cancer cell growth was markedly suppressed by SCD1 inhibitors only in EGFR-activated cells." (PMID 28724430, 2017). "A better understanding of the metabolic plasticity or dysregulated metabolic reprogramming of cancer cells may help us to elucidate how they contribute to resistance to conventional chemo- and radiation therapies and EGFR-targeted therapies." (PMID 27926487, 2017). "MDA-MB-231, MDA-MB-468 and BT-20 are TNBC cancer cell lines that express wild-type EGFR." (PMID 28593948, 2017). "Studies have demonstrated that cancer specific alterations in signaling pathways for EGFR/HER2, ERK, insulin growth factor system may lead to HSF1 activation via post translation modification." (PMID 28914774, 2017). "Additionally, we observed an anti-cancer effect of anti-EGFR-GNs in another TNBC cell line, MDA-MB-468." (PMID 29156817, 2017). "EGFR is particularly important as a therapeutic target for cancer treatments." (PMID 29021557, 2017). "A fenugreek extract decreased the phosphorylation of EGFR induced by TGFβ in PC-3 cancer cells." (PMID 28694778, 2017). "TGFα-PE38 should be effective against EGFR-expressing cancer cells." (PMID 28473665, 2017). "Although recent studies show the co-overexpression of XIAP and EGFR in many cancers, and the high sensitive to anti-IAPs therapy if the cancers with EGFR overexpression, a possible association of XIAP with EGFR overexpression has never been explored in previous studies." (PMID 28057023, 2017). "Several new associations with ETS negative cancers were found, including deletions at 1q42.2-q42.3 & 4q22.3, and amplifications at 3q22.1-q21.3, 7p11.2 (EGFR), & 8q (MYC)." (PMID 28945760, 2017). "Therefore, in the development of new drugs for cancer treatment, EGFR and its signaling components can be used as targets, such as chimeric monoclonal antibodies (panitumumab and cetuximab) and TKIs (gefitinib, erlotinib, and afatinib)." (PMID 28430586, 2017). "These two clinical trials suggest that T cells engineered with properly selected CARs targeting HER2 or EGFR could be safely used in cancer patients with high HER2 or EGFR expression." (PMID 28434147, 2017). "Targeting dimerization of EGFR will have a significant impact on cancer therapies." (PMID 29088782, 2017). "Furthermore, there are only some reports about the effect of CAFs on intrinsic resistance against EGFR-TKIs21, 23, both of which report CAFs as a factor that makes cancer cells more resistant to these inhibitors." (PMID 28429795, 2017). "This cancer has been linked to mutations in EGFR for never-smokers and mutations in kRAS for smokers." (PMID 29113413, 2017). "In this way, nuclear EGFR signaling represents another way by which the EGFR promotes cell cycle progression, highlighting the breadth and redundancy of the EGFR signal transduction network in cancer progression." (PMID 28513565, 2017).
cancer (continued). "Patients with EGFR mutations or ALK-fusions are recommended to receive targeted therapy of tyrosine kinase inhibitors (TKIs), which significantly prevents the progression of cancer and improves patients’ prognosis." (PMID 29285248, 2017). "PEG engagerEGFR significantly enhanced the anti-proliferation activity of Doxisome and PEG-liposomal vinorelbine against EGFR-positive cancer cells as compared with drug-loaded nanocarrier alone, drug-loaded nanocarrier plus PEG engagerCD19 or empty liposomes with PEG engagerEGFR." (PMID 28593948, 2017). "Therefore, potential cancer treatments that modulate EGFR pathway activity have been extensively studied." (PMID 27935858, 2017). "urokinase-type Plasminogen Activator Receptor (uPAR), Tissue Factor (TF) and Epidermal Growth Factor Receptor (EGFR) are three biomarkers that exhibit enhanced expression in many types of cancers, and have been investigated as potential biomarkers for targeted strategies and prognostication." (PMID 28841839, 2017). "The high sensitivity of EGFR or HER2 overexpressing cancer cells to DDAs may derive from the large number of disulfide bonds in these proteins combined with the ability of DDAs to prevent the formation of Disulfide bonds in the ER." (PMID 28423644, 2017). "In addition, the PNA probe design can be modified in the detection of other somatic mutations, such as EGFR, KRAS, or BRAF mutations in many cancers." (PMID 29104223, 2017). "Thus, canine anti‐EGFR IgG has been generated 117 and IgE is currently being generated for comparative studies in canine cancer patients." (PMID 28032353, 2017). "Indeed, a linear correlation was observed between the logarithm of EGFR expression levels on cancer cell lines and the logarithm of the anti-proliferative activity (EC50 values) of PEG engagerEGFR plus Doxisome treatment (R2=0.702)." (PMID 28593948, 2017). "Interestingly, short interfering RNA (siRNA)-mediated REP1 knockdown-induced growth inhibition of cancer cell lines via downregulation of EGFR and inactivation of STAT3, but had a negligible effect on normal cell lines." (PMID 28230863, 2017). "Recent data have shown that EGFR-specific CD8+ T cells may contribute to clinical response in cancer patients treated with anti-EGFR mAbs." (PMID 29056908, 2017). "Recently, researchers have realized the importance of EGFR gene polymorphims in cancer therapy." (PMID 29156842, 2017). "Thus, combining the antioxidant CAT-SKL with erlotinib targeted both CSCs and bulk cancer cells in cultures of EGFR-expressing TNBC-derived cells." (PMID 28281569, 2017). "Epithelial growth factor (EGF), via its receptor EGFR, elicits proliferation in many human cancers." (PMID 29137335, 2017). "In the cancer setting, it has been recently reported that EGFR downregulates the expression of APM components and HLA class I via activation of protein phosphatase type 11 (PTNP11) best known as SHP2 which dephosphorylates signal transducer and activator of transcription 1 (STAT1)." (PMID 28611673, 2017). "Although EGFR dysregulation enhances cancer metastasis, the relevant downstream effectors are largely unknown." (PMID 28703807, 2017). "EGFR-targeting drugs directly affect cancer cells and may be affected by accumulating drug resistance mutations in the RAS-RAF-MEK-ERK pathway." (PMID 28368335, 2017). "This novel anti-EGFR mAb, EMab-134, could be advantageous for detecting EGFR in the pathological analysis of EGFR-expressing cancers." (PMID 29090976, 2017). "The recent progresses in the knowledge of the molecular mechanisms of GEF resistance have identified that the altered expression and activity of Ras and Raf, the down-stream signaling molecules of EGFR, exert a critical role in the resistance of cancer cells to GEF." (PMID 26461472, 2017). "Moreover, we also found that CNG of EGFR, HER2, HER3 and HER4 was correlated with the risk of cancer-related death in female patients." (PMID 29190914, 2017).